TRIM47 (tripartite motif containing 47)
Diseases named in the same sentence as TRIM47 in open-access papers (continued):
Sharing a sentence is not in itself a finding about the gene and the disease.
lymph node metastasis (1 paper, 2017). "Multivariate Cox regression analyses showed that along with TNM stage and lymph node metastasis, overexpression of TRIM47 (P = 0.017) could be considered an independent prognostic factor for NSCLC patients." (PMID 28186994, 2017).
nonalcoholic steatohepatitis (1 paper, 2022). "TRIM47 is also known to contribute to pathogenesis of nonalcoholic steatohepatitis (NASH) by causing ubiquitination and degradation of a protein called cylindromatosis (CYLD)." (PMID 35954308, 2022).
osteosarcoma (1 paper, 2025). A usually aggressive malignant bone-forming mesenchymal neoplasm, predominantly affecting adolescents and young adults. "More notably, our in vivo assays showed that loss of TRIM47 slowed the growth rate of osteosarcoma xenograft tumours." (PMID 40801794, 2025). "In this study, we unveiled the clinical significance, biological functions, as well as underlying mechanisms of TRIM47 in osteosarcoma carcinogenesis and progression." (PMID 40801794, 2025). "Taken together, TRIM47 is frequently upregulated and positively associated with poor clinical outcomes of osteosarcoma patients." (PMID 40801794, 2025). "In addition, the TRIM47 upregulation was positively associated with aggressive clinical stage and worse overall survival, indicating its role as a prognostic marker in osteosarcoma." (PMID 40801794, 2025). "Moreover, the mutation frequency of TRIM47 in osteosarcoma was up to 5%." (PMID 40801794, 2025). "Through cell proliferation, colony formation, migration and invasion, and wound healing assays, we found that upregulation of TRIM47 promoted the proliferation, migration, and invasion of osteosarcoma cells." (PMID 40801794, 2025). "The immunostaining of TRIM47 in osteosarcoma tissues was much higher than that in adjacent non‐cancerous tissues." (PMID 40801794, 2025). "Cellular experiments revealed that TRIM47 accelerates the proliferation and invasion of osteosarcoma cells in vitro, and TRIM47 depletion elicited opposite effects." (PMID 40801794, 2025). "To elucidate the impact of TRIM47 on osteosarcoma carcinogenesis more credibly, we constructed the subcutaneous tumour formation model to evaluate the tumour cell growth in vivo." (PMID 40801794, 2025). "Consistently, the TRIM47 protein expression was found to be frequently overexpressed in eight fresh osteosarcoma tissues when compared with normal sarcoma tissues (6/8, 75%)." (PMID 40801794, 2025). "In the present research, we firstly identified that TRIM47 served as a novel positive regulator of the Wnt/β‐catenin pathway in osteosarcoma." (PMID 40801794, 2025). "Collectively, TRIM47 knockdown impeded the tumour growth of osteosarcoma cells via regulating the FBP1‐β‐catenin axis in vivo." (PMID 40801794, 2025). "TRIM47 was drastically overexpressed, positively correlated with clinical pathological grade, and poor prognosis in osteosarcoma patients." (PMID 40801794, 2025). "In summary, our study unveils TRIM47 as a bona fide activator of the Wnt/β‐catenin pathway to facilitate osteosarcoma tumourigenesis and progression via ubiquitinating FBP1 protein." (PMID 40801794, 2025). "Tripartite motif containing 47 (TRIM47) upregulation contributed greatly to carcinogenesis and progression in several tumours, while its role in osteosarcoma (OS) is still unclear and needs further investigation." (PMID 40801794, 2025). "To determine the effect of TRIM47 on the migratory and invasive ability of osteosarcoma cells, we utilised wound healing and transwell assays in osteosarcoma cells." (PMID 40801794, 2025). "In this study, we first evidenced that TRIM47 was frequently upregulated in osteosarcoma tissues and cell lines, and the higher TRIM47 expression predicted poor outcomes for osteosarcoma patients." (PMID 40801794, 2025). "Here, we found that TRIM47 was frequently upregulated in osteosarcoma tissues." (PMID 40801794, 2025). "Since TRIM47 might function as an aggressive biomarker of OS patients, we further investigated the cellular roles of TRIM47 in the malignant processes of osteosarcoma via knockdown experiments." (PMID 40801794, 2025). "On the contrary, overexpression of TRIM47 revealed the opposite effects in osteosarcoma cells." (PMID 40801794, 2025). "Moreover, TRIM47 was essential in sustaining cell proliferation, migration, and invasion in osteosarcoma cells." (PMID 40801794, 2025). "Correlation between TRIM47 expression and clinicopathological factors of osteosarcoma patients." (PMID 40801794, 2025).
osteosarcoma (continued). "Furthermore, the protein and mRNA expression of TRIM47 was also upregulated in osteosarcoma cell lines." (PMID 40801794, 2025). "Moreover, TRIM47 depletion impeded cell proliferation, migration, and invasion of osteosarcoma cells, while TRIM47 overexpression elicited opposite effects." (PMID 40801794, 2025). "However, the molecular mechanisms by which TRIM47 exerts oncogenic roles in osteosarcoma still need to be further investigated." (PMID 40801794, 2025). "However, the detailed interplays linking TRIM47 and Wnt/β‐catenin in osteosarcoma remain uninvestigated." (PMID 40801794, 2025). "Moreover, our survival analysis indicated that the overall survival of patients with high TRIM47 expression was much worse than that of those with low TRIM47 expression (p < 0.05), indicating that TRIM47 may function as a prognostic marker for osteosarcoma patients." (PMID 40801794, 2025). "Mechanistically, TRIM47 reduced the protein stability of fructose 1, 6‐bisphosphatase 1 (FBP1), thereby triggering the activation of the Wnt/β‐catenin pathway, ultimately leading to tumorigenesis and progression of osteosarcoma." (PMID 40801794, 2025).
sarcoma (1 paper, 2025). A usually aggressive malignant neoplasm of the soft tissue or bone. "Interestingly, TRIM47 expression was upregulated in a range of tumour types, including sarcoma." (PMID 40801794, 2025).
thyroid (1 paper, 2025). "Based on the analysis of our data above, we would like to claim that TRIM47 promotes thyroid tumorigenesis via the downregulation of ADAR, which is consistence with both the thyroid carcinoma tissues and the cultured TC cells." (PMID 40618019, 2025). "In our study, the results indicated TRIM47 endorses thyroid tumorigenesis via the down-regulation of ADARviaTRIM47/ADAR axis as well, which involved GSK-3β mediated phosphorylation." (PMID 40618019, 2025). "To comprehend the cellular mechanism of TRIM47 in thyroid tumorigenesis, we carried out mass spectrometry with the precipitation of immunoprecipitation (IP) TRIM47 complex and further made sure of their transcription level of components of the complex with mass spectrometry." (PMID 40618019, 2025).
thyroid cancer (1 paper, 2025). "Our detailed experiments depict a novel mechanism which is TRIM47 promoted the development of thyroid carcinoma via ADAR-associated ubiquitination, and GSK-3β mediated phosphorylation on both/either TRIM47 and ADAR was critical for TRIM47 suppression." (PMID 40618019, 2025). "According to our experiments and analysis above, we claimed that TRIM47 promoted the growth of thyroid cancer cells, and deleting expression by TRIM47 knocking-down enhanced the chemo-sensitivity of thyroid cancer cells." (PMID 40618019, 2025). "Through examinations within experiments in vitro and in vivo, we unveiled that TRIM47 significantly suppressed the growth in the clinical samples of thyroid carcinoma, TC tumor cell lines, and xenograft animal models." (PMID 40618019, 2025). "Tripartite motif 47 (TRIM47) plays a vital role in the carcinogenesis and drug resistance of various cancers, whereas the function of TRIM47 in thyroid carcinoma (TC) remains unclear." (PMID 40618019, 2025). "Thus, we would like to claim that the alternation of the expression of TRIM47 relates to clinicopathological features of thyroid carcinoma." (PMID 40618019, 2025). "The novel interaction between TRIM47-ADAR may certainly shed new light in the field of thyroid carcinoma study and inspire future exploration of the potential significance in TC patient treatment." (PMID 40618019, 2025). "The stability and regulation of the TRIM47-ADAR-GSK-3β axis could determine the exacerbation of TC tumor expansion, invasion, and metastasis in tumor model animals and patients at high risk of thyroid carcinoma." (PMID 40618019, 2025). "Furthermore, we overexpressed HA-ADAR and Flag-TRIM47 in human embryonic kidney HEK-295 T cells and also approved the interaction between ADAR and TRIM47 in non-thyroid carcinoma cell lines." (PMID 40618019, 2025). "70.8% of the samples increased in protein levels of TRIM47 in tissues of thyroid carcinoma than in non-cancerous tissues." (PMID 40618019, 2025).
tumor (23 papers, 2017 to 2026). "Here, we found that TRIM47 was upregulated in tumor tissues and associated with poor clinical outcomes of HCC patients." (PMID 39567506, 2024). "Clinically, elevated TRIM47 expression strongly correlates with advanced tumor stage, metastasis, and poor prognosis, establishing its robust potential as a pan-cancer predictive biomarker." (PMID 42292357, 2026). "By establishing a subcutaneous xenograft model in immunodeficient nude mice, we further demonstrated that TRIM47 knockdown in LC cells can inhibit tumor proliferation, lead to G2/M cell cycle retardation and induce cell apoptosis, and vice versa." (PMID 41460629, 2025). "Analysis of the Clinical Proteomic Tumor Analysis Consortium (CPTAC) database revealed that the protein expression levels of TRIM47 were significantly elevated in primary tumor tissues (n = 165) compared to normal liver tissues (n = 165)." (PMID 41460629, 2025). "The activation of related pathways was subsequently confirmed in TRIM47-overexpressed Hep3B tumor tissues." (PMID 41460629, 2025). "Many studies outside ICC have shown that TRIM47 promotes tumor cell proliferation and inhibits tumor cell apoptosis." (PMID 41380966, 2025). "After treatment with BAY-11-7082, a specific inhibitor of the NF-κB pathway, the tumor-promoting effect of TRIM47 was significantly inhibited in Huh7 cells." (PMID 41460629, 2025). "The expression of Ki67 was reduced in the tumor tissues with TRIM47 knockdown, indicating that tumor proliferation was inhibited." (PMID 41380966, 2025). "First, we examined the protein expression of PLK1 in three stable LC cell lines and subcutaneous tumor tissues, and the results revealed a significant positive correlation between TRIM47 and PLK1 protein expression levels." (PMID 41460629, 2025). "Functionally, TRIM47 knockdown suppressed LC cell growth, while its overexpression promoted tumor proliferation." (PMID 41460629, 2025). "Upon the TRIM47 silencing, the tumor was smaller and the obsessive consequences were better with fewer metastatic nodules in the lung after 28 days of the cells xenografted." (PMID 40618019, 2025). "The successful knockdown and overexpression of TRIM47 was verified by examining its expression in the tumor tissues." (PMID 41380966, 2025). "Functional studies indicated that TRIM47 knockdown in ICC cells suppressed cell growth in vitro and the tumorigenicity of tumor cells in vivo, whereas TRIM47 overexpression had the opposite effect." (PMID 41380966, 2025). "The consequences of the animal model indicated that TRIM47 knocking-down lessened the tumor size of the nude mice." (PMID 40618019, 2025). "Our data on subcutaneous tumors induced with inoculation of THJ-29 T cells in nude mice showed that the tumor grew significantly slower and smaller in response to TRIM47 silencing." (PMID 40618019, 2025). "Parallel experiments with TRIM47-overexpressed tumor cells revealed a significantly enhancement in tumor growth compared to the control group, with tumor volume and weight measurements showing consistent results between both cell models." (PMID 41460629, 2025). "TRIM47, a member of the tripartite motif-containing E3 ligase family, has been shown to promote tumor cell proliferation and migration by stabilizing PARP1 through K63-linked ubiquitination, thereby enhancing AKT pathway activity." (PMID 40564091, 2025). "This study discovered that TRIM47 was significantly suppressed in TC clinical samples and tumor cell models." (PMID 40618019, 2025). "Elevated TRIM47 levels are associated with poor prognosis and LNM, suggesting its role in driving tumor aggressiveness via post-translational modification." (PMID 40564091, 2025).
tumor (continued). "TRIM47 was upregulated in HCC tumor tissues compared with normal tissues, especially at advanced stages (stage IV vs stage I/II/III in TCGA)." (PMID 39567506, 2024). "It has been demonstrated that TRIM47 has E3 ligase activity, which is likely to play a role in tumor occurrence and prognosis." (PMID 36534449, 2022). "TRIM47 is frequently overexpressed in human cancers and promotes tumor cell proliferation and metastasis." (PMID 36288633, 2022). "It was found that the expression level of KCTD12, SIAH1, TRIM58, UBE2S, and UBE2T were significantly decreased in tumor tissue compared with the normal tissue, but TRIM47 was upregulated." (PMID 36534449, 2022). "Mcl-1, MMP2, and c-Myc mRNA levels were also reduced in the xenograft tumor tissues with TRIM47 knockdown." (PMID 36288633, 2022). "Research shows tumor tissues express TRIM47 at a higher level than normal tissue, which is consistent with our findings." (PMID 36534449, 2022). "The xenografts of the TRIM47 knockdown group grew slower and its tumor weight was also smaller than that in the control group." (PMID 36288633, 2022). "GEPIA and TIMER datasets were applied to analyze the differential levels of TRIM47 in various tumor and adjacent normal tissues." (PMID 33833824, 2021). "Previous studies demonstrate that tumor tissues highly express TRIM47, compared to normal adjacent tissues." (PMID 33833824, 2021). "The results of the animal model showed that the use of Crispr/cas9 technology to knock out TRIM47 reduced the tumor-bearing ability of nude mice." (PMID 33622324, 2021). "The role of TRIM47 as a tumor-promoting molecule in promoting the malignant biological behavior of RCC is crucial." (PMID 33622324, 2021). "In support of the pro-tumor role of TRIM47, the Ki67 staining showed that knockdown of TRIM47 decreased tumor cell proliferation in vivo." (PMID 30979374, 2019). "TRIM47 was localized to 17q24–25, a region that is frequently gained or amplified in a number of other tumor types." (PMID 30979374, 2019). "We found that tumor growth was significantly decreased by 5-FU treatment, and these decreases were blocked by TRIM47 overexpression adenovirus treatment in vivo." (PMID 30979374, 2019). "Then, we found that TRIM47 silencing inhibited cell proliferation, migration, invasion and xenograft tumor growth." (PMID 28186994, 2017). "We found that TRIM47 knockdown significantly inhibited the tumor growth rate in nude mice (P < 0.01)." (PMID 28186994, 2017). "TRIM47 expression was correlated with tumor differentiation (P = 0.011), TNM stage (P = 0.002), lymph node metastasis (P = 0.003), and tumor size (P = 0.016)." (PMID 28186994, 2017). "TRIM47 mRNA levels were significantly increased in tumor tissues compared with normal adjacent tissues." (PMID 28186994, 2017). "In this study, we found that tripartite motif containing 47 (TRIM47) expression level was higher in tumor tissues than in normal adjacent tissues." (PMID 28186994, 2017). "High TRIM47 expression levels correlated with tumor differentiation, TNM stage, lymph node metastasis and tumor size." (PMID 28186994, 2017). "To verify the positive role of TRIM47 on tumorigenicity in vivo, we performed xenograft tumor assays using A549 cells stably infected by scramble shRNA control or TRIM47-shRNA lentiviruses." (PMID 28186994, 2017). "In conclusion, we demonstrated that TRIM47 is an important tumor-promoting factor in LC." (PMID 41460629, 2025).